IL5 (interleukin 5)
Diseases named in the same sentence as IL5 in open-access papers (continued):
Sharing a sentence is not in itself a finding about the gene and the disease.
COVID-19 (continued). "In our study, we detected a significant increase in IL-5 production levels by PBMCs but not by neutrophils, which may indicate that PBMCs may be responsible, in part, for the elevated serum levels of IL-5 in COVID-19 ICU patients." (PMID 36363785, 2022). "Conversely, significantly higher levels of GM-CSF, IFN-β, IL-10, and IL-2 and low levels of Eotaxin, IL-4, IL-5, MCP-1, and MIP-1β, were distinctive to Non-SOT COVID-19 patients relative to HCs, but not in SOTRs." (PMID 35075453, 2022). "While the levels of IP-10, IL-15 and IL-18 were exclusively increased in SOTRs with COVID-19, Non-SOT patients with COVID-19 showed solely higher levels of IFN-β, IL-2, IL-10, GM-CSF and low levels of Eotaxin, MCP-1, MIP-1β, IL-4, IL-5." (PMID 35075453, 2022). "We investigated the circulating levels of IFNγ, IL-4, sIL-4R, IL-5, IL-9, IL-17A, IL-17F, IL17-E/25, IL-22 and sCD30 in surviving and non-surviving severe COVID-19 patients and healthy controls." (PMID 36142255, 2022). "On the other hand, some markers (i.e., IL-5, IL-7, IL-17A, CXCL8, and VEGF) were increased in critical COVID-19 patients only and not in macrophage activation syndrome." (PMID 35645351, 2022). "Moreover, the IL-15 immunotherapy may be a feasible strategy for COVID-19, as it induces innate immune responses via the induction of NK cells, CD8+ T cells, and T regulatory cells to neutralize Th2 cytokine storms, leading to decreased levels of IL-4, IL-5, and IL-13." (PMID 35679246, 2022). "Levels of IL-5 were not significantly influenced by SARS-CoV-2 infection, whereas IL-33 was increased in patients with severe and critical COVID-19 but not in patients who died from COVID-19." (PMID 33232303, 2021). "Healthy pregnant women showed high levels of interleukins including IL-2, IL-5, IL-10, and IL-12, as well as high levels of growth factors such as b-NGF and VEGF, which were largely decreased in COVID-19 pregnant and non-pregnant patients." (PMID 34012458, 2021). "Proinflammatory molecules, such as IL-2, IL-4, IL-5, IL-6, IL-10, IL-13, TNF-α, IFN-Υ, and CRP, were found at higher levels in COVID-19 patients with DM than in COVID-19 patients without DM." (PMID 34786431, 2021). "Also, while both IL-5 and ALAS2 were enriched in group 4, IL-5 appeared to have no significant role in COVID-19." (PMID 41839673, 2025). "Serum inflammatory factor levels of IL-2, IL-1β, IL-5, IL-4, IL-6, IL-8, IL-10, IL-17, IL-12P70, IFN-α, TNF-α, IFN-γ, endotoxin, CRP, and hs-CRP of non-severe COVID-19 patients across different age groups (< 50, 50–60, 60–70, and ≥ 70 years) were not significantly different." (PMID 33065551, 2020).
airway hyperresponsiveness (127 papers, 2006 to 2026). "We demonstrate that camel milk suppresses airway hyperresponsiveness, Th2 and Th17 cell recruitment, and associated cytokines (IL-4, IL-5, IL-13, IL-17A), while reducing dendritic cell activity and CCL17 expression in the lungs." (PMID 40577410, 2025). "The combination of IL-6 and IL-8 is frequently used in ARDS research, whereas IL-13 was only present in combination with high IL-5 concentrations; both are T-helper cell 2 cytokines associated with airway hyperresponsiveness." (PMID 31998415, 2020). "As a result, Th2 cells increase in T-bet-deficient mice and spontaneously help to form airway hyperresponsiveness associated with overproduction of Th2 cytokines (IL-4, IL-5 and IL-13) and to cause infiltration of eosinophils and lymphocytes." (PMID 32489402, 2020). "Type 2 cytokines such as IL-4, IL-5, and IL-13 cause airway hyperresponsiveness, mucus secretion, and eosinophil aggregation and induce B lymphocyte to produce IgE-mediated allergic reaction." (PMID 31737687, 2019). "In SP‐D‐deficient OVA‐challenged mice, airway hyperresponsiveness was significantly enhanced despite the lower eosinophil count and the concentration of interleukin (IL)‐5 and IL‐13 in BALF compared with WT OVA‐challenged mice at 120 ventilations per minute." (PMID 29368450, 2018). "The allergic form is an adaptive T helper 2-driven disease characterized by elevated levels of interleukin (IL)-5, interleukin-4 (IL-4), and IL-13, associated with enhanced levels of circulating and lung eosinophils, elevated serum IgE, mucus hypersecretion and airway hyperresponsiveness." (PMID 34744763, 2021). "This immunoregulatory action might have resulted in a reduction of inflammation and airway hyperresponsiveness associated with the downregulation of IL-5, IL-6, and IL17." (PMID 23533467, 2013). "IL-4, IL-5, IL-6, and IL-13 have been shown to maintain this cycle of allergic inflammation with IL-4 promoting Ig isotype switching, IL-5 inducing eosinophil differentiation and migration, and IL-13 causing goblet cell hyperplasia and airway hyperresponsiveness." (PMID 30380761, 2018). "In an animal study providing IL-12 to mice previously exposed to an antigen, airway hyperresponsiveness and pulmonary eosinophilia were eliminated, and the expression of IL-4 and IL-5 was diminished." (PMID 41155381, 2025). "IL-4 and IL-5 are key cytokines that promote eosinophilic inflammation and mast cell activation, and elevated levels of both contribute to airway hyperresponsiveness, exacerbating the progression of BA." (PMID 40951891, 2025). "While IL‐13 is known to induce tissue remodeling, airway hyperresponsiveness, and mucus secretion in the lung, IL‐5 is a key stimulus for the recruitment and survival of eosinophils." (PMID 39955650, 2025). "In our investigation, the choice of indicators, including airway hyperresponsiveness, cytokine concentrations (IL-4, IL-5, and IL-13), IgE titers, and histopathological examinations, was pivotal for evaluating the efficacy of hydrogen therapy." (PMID 41146240, 2025). "In SA, epithelial-derived cytokines play a central role in initiating and sustaining type 2 (T2) inflammation by activating the IL-4, IL-5, and IL-13 axis, leading to increased eosinophils, elevated serum IgE, and heightened airway hyperresponsiveness." (PMID 41169790, 2025). "More data on airway hyperresponsiveness are still needed for anti-IL-5 therapy, but a recent phase 4 clinical trial revealed reduced airway hyperresponsiveness in patients with severe eosinophilic asthma treated with benralizumab." (PMID 41145900, 2025). "In the lung, they release IL-5 and IL-13 and activate eosinophilic lung accumulation, calcination, mucus aggregation, epithelial interstitial reaction, and finally pulmonary airway hyperresponse and airway remodeling." (PMID 39015676, 2024).
airway hyperresponsiveness (continued). "In comorbid eosinophilic asthma and CRSwNP, eosinophils, under the action of type 2 cytokines including IL-5, significantly contribute to airway hyperresponsiveness, inflammation, epithelial cell damage, remodeling, and clinical exacerbations." (PMID 39338268, 2024). "I.n. challenge of sensitized animals led to increased BAL type 2 cytokines (IL-4, IL-5 and IL-13) as well as airway hyperresponsiveness." (PMID 39157265, 2024). "With the addition of microcapsules, the bread effects were more pronounced, with a significant reduction in airway hyperresponsiveness, percentage of eosinophils, and Th2 cytokines concentrations (IL5 and IL13), and an increase in the IL17A concentrations." (PMID 38655128, 2024). "When they gave anti-TSLP monoclonal antibody, the DEHP enhanced airway inflammation, Th2 cytokines (IL-4, IL-5 and IL-13) production, and airway hyperresponsiveness were reduced via neutralized TSLP." (PMID 37545493, 2023). "It has been shown that through the activation of IL-5 and IL-13 secretion, IL-33 promotes airway hyperresponsiveness." (PMID 37107767, 2023). "IL-4 plays a key role in Th2 cell differentiation, while IL-5 is specifically involved in eosinophilic inflammation and airway hyperresponsiveness." (PMID 36755351, 2023). "In allergic asthmatic mice, GPER agonist attenuated airway hyperresponsiveness, inflammatory cell accumulation, and Th2 cytokine production (IL-5 and IL-13) in BAL fluid." (PMID 36142703, 2022). "TSLP can stimulate the activation and proliferation of ILC2s to produce a large amount of IL-5 and IL-13, resulting in airway inflammation and airway hyperresponsiveness." (PMID 36482599, 2022). "Resveratrol significantly attenuated the level of Th2 cytokines such as IL-4 and IL-5 in plasma and bronchoalveolar lavage fluid and also effectively suppressed airway hyperresponsiveness and mucus hypersecretion, in the asthmatic mouse model." (PMID 35796922, 2022). "Using an airway hyperresponsiveness mice model, one study showed that PS-F2 inhibited airway hyperresponsiveness via reducing Th2 cytokines, interleukin (IL)-4, IL-5, and IL-13." (PMID 34681911, 2021). "Studies have shown that IL-5 mediated eosinophil infiltration in the trachea is a prerequisite for airway hyperresponsiveness." (PMID 32395767, 2020). "The pollutants also stimulate ILC2 to produce IL-5 and IL-13, thereby increasing airway hyperresponsiveness." (PMID 31269777, 2019). "These pollutants and carbon nanotubes stimulate lung ILC2s, produce high levels of interleukin (IL)-5 and IL-13, and induce airway hyperresponsiveness." (PMID 31269777, 2019). "IL-13, IL-1 β, IL-6, IL-4, IL-5 are Th2 cell-type factors, mainly involved in mucus secretion, eosinophil production, IgE synthesis, and airway hyperresponsiveness." (PMID 31024302, 2019). "In the present study, T. IIA inhibited the infiltration of inflammatory cells in the lung, reduced the productions of IL-4, IL-5, and IL-13, and dampened airway hyperresponsiveness." (PMID 30834081, 2019). "In humans, IL-5 is highly specific for eosinophilic inflammation, and antibodies which block IL-5 actions are effective in reducing eosinophilic inflammation and airway hyperresponsiveness." (PMID 31694631, 2019). "TH2-high patients are characterized by the expression of IL-5 and IL-13, airway hyperresponsiveness, responsiveness to inhaled corticosteroids (ICS), high serum IgE levels, and blood and airway eosinophilia." (PMID 28913336, 2017). "AS-IV markedly suppressed airway hyperresponsiveness and reduced IL-4, IL-5, and IL-17 levels and increased INF-γ levels in the BALF." (PMID 29234390, 2017). "IVE and AET ameliorated OVA-driven airway hyperresponsiveness (p < 0.01), pulmonary eosinophilic infiltration (p < 0.05), mucus hypersecretion (p < 0.01), and IL-4, IL-5, IL-13, and CCR3 production (p < 0.05), as well as IgE levels (p < 0.01)." (PMID 29062168, 2017).
airway hyperresponsiveness (continued). "Accordingly, after re-exposure to the antigen challenge, ovariectomized allergic mice showed exacerbated allergic inflammation, airway hyperresponsiveness, and excess secretion of mucus and the cytokine IL-5." (PMID 28959241, 2017). "Strikingly, administration of G-1 attenuated airway hyperresponsiveness, accumulation of inflammatory cells, and levels of Th2 cytokines (IL-5 and IL-13) in BAL fluid." (PMID 25826377, 2015). "After the first challenge, antigen exposure induced a transient airway obstruction and airway hyperresponsiveness, high levels of IL-4 and IL-5 in lung and airway globet cells proliferation at the third antigenic challenge." (PMID 25977751, 2015). "IL-5 mRNA levels in asthmatics has a high correlation with eosinophils, airway hyperresponsiveness, and exhaled nitric oxide levels, which reflect airway inflammation." (PMID 25264130, 2014). "KWLL reduced Der p-induced airway hyperresponsiveness and inhibited eosinophil infiltration by downregulating the protein expression of IL-5 in bronchoalveolar lavage fluid (BALF)." (PMID 23533467, 2013). "The participation of IL-5 in stimulating eosinophils to induce airway hyperresponsiveness is clear, once depletion of eosinophils with antibody to IL-5 leads to blockage of hyperresponsiveness." (PMID 23616768, 2013). "PIO and DEX demonstrated similar abilities to reduce airway hyperresponsiveness, pulmonary recruitment of inflammatory cells, serum IgE, and lung levels of IL-4, IL-5, TNF-α, TGF-β, RANTES, eotaxin, MIP3-α, Gob-5, and Muc5-ac." (PMID 18053220, 2007). "IL-4 and IL-5 regulate the maturation and release of eosinophils in the bone marrow, while IL-13 promotes B cell differentiation and plays a leading role in airway inflammation, airway hyperresponsiveness, and mucus secretion." (PMID 40070820, 2025). "At the physiological level, biologic therapies contribute to the reduction in type 2 inflammation by targeting specific cytokines (IL-4, IL-5, IL-13) and IgE, leading to decreased airway hyperresponsiveness, reduced mucus production, and improved lung function." (PMID 41302212, 2025). "In addition, airway eosinophils are activated by IL-5 to promote degranulation, and airway hyperresponsiveness, inflammation, and remodeling are affected by IL-13." (PMID 36296620, 2022). "Our results showed that lonicerin significantly reduced airway hyperresponsiveness the number of inflammatory cells (especially eosinophils) and the elevation of interleukin (IL)-4, IL-5, IL-13 and eotaxin in bronchoalveolar lavage fluid (BALF) supernatants of mice." (PMID 36618942, 2022). "Increased airway hyperresponsiveness after EC vapor inhalation.Increased infiltration of inflammatory cells, including eosinophils, into airways from blood.Stimulation of production of Th2 cytokines such as IL-4, IL-5 and IL-13 and allergen-specific IgE." (PMID 34442368, 2021). "In addition, it also induced eosinophilic inflammation, the production of IL-4, IL-5, IL-13, and IL-33 in bronchoalveolar lavage fluid, and airway hyperresponsiveness." (PMID 34079051, 2021). "In the present study, we provide evidence that IL-33 exacerbates antigen-induced asthmatic responses, including airway hyperresponsiveness, inflammation and remodeling, mast cell activation, production of IgE and cytokines including IL-4, IL-5 and IL-13, and accumulation of pulmonary ILC2s." (PMID 28652606, 2017). "IL-5 also stimulates eosinophilic airway inflammation and airway hyperresponsiveness." (PMID 28913336, 2017). "In addition, reduced airway hyperresponsiveness, IL-5 levels, and mucus production were also observed." (PMID 28959241, 2017). "T helper type 2 immune responses such as high levels of IL-4 versus IFN-γ and the release of IL-5 and IL-13 cytokines are known to contribute to eosinophil recruitment to the lung, goblet cell formation from epithelial cells, mucus production and airway hyperresponsiveness." (PMID 25658239, 2015).
airway hyperresponsiveness (continued). "Treatment of mice with the C. elegans crude extract significantly decreased methacholine-induced airway hyperresponsiveness and the total cell counts and levels of IL-4, IL-5 and IL-13 in the bronchoalveolar lavage fluid but increased the levels of IFN-γ and IL-12." (PMID 22558152, 2012). "In contrast, other studies have shown that anti-IL-5 blocks eosinophilic influx into the lungs, although hardly any effect on airway hyperresponsiveness could be observed." (PMID 16597326, 2006). "Therefore, one explanation to our results is that our read-out time point at 48h to acquire the highest response in HDM-induced airway hyperresponsiveness (based on our unpublished data) may occur later than the peak of IL-5 and IL-13 production in lung." (PMID 26214807, 2015). "Prebiotic intervention significantly reduced airway hyperresponsiveness (AHR) and type 2 cytokines (IL-4, IL-5, IL-13) and various cell counts, including neutrophil, macrophage, lymphocyte, eosinophil, and total bronchoalveolar (BALF)." (PMID 41754200, 2026). "The eosinophilic response to allergens and the resultant airway hyperresponsiveness (AHR) are significantly reduced in IL-5 gene knockout mice, confirming the efficacy of the method of suppressing IL-5." (PMID 40136649, 2025). "Compared to WT mice, NLRP3-/- mice displayed significantly increased airway hyperresponsiveness (AHR), mucus production, and elevated systemic levels of IL-5 and IL-13." (PMID 41394833, 2025). "Then airway hyperresponsiveness (AHR), eosinophil percentage, levels of interleukin (IL)‐33, IL‐25, IL‐13, IL‐5, IL‐4, total and ovalbumin (OVA)‐specific immunoglobulin (Ig)E, and lung histopathology were evaluated." (PMID 38664220, 2024). "Sphingosine kinase inhibitor reduced inflammatory cell infiltrates, IL‐4, IL‐5, and eotaxin levels in BAL fluid, and suppressed airway hyperresponsiveness." (PMID 38342758, 2024). "Most importantly, intratracheal instillation of shikonin can down-regulate the release of IL-4, IL-5, IL-13, and TNF-α in BALF and reduce pulmonary eosinophils and airway hyperresponsiveness." (PMID 39444792, 2024). "IL-5, IL-13, and ovalbumin (OVA) specific IgE and airway hyperresponsiveness (AHR) are also responsible for mitochondrial dysfunction and thus conclude that Th2-dominant response enhances mitochondrial oxidative stress in airways." (PMID 35796922, 2022). "In Tlr9–/– mice, airway hyperresponsiveness (AHR) and the number of eosinophils decreased, and production of the Th2 cytokines IL-13, IL-5, and IL-4 was suppressed, compared with in wild-type mice." (PMID 33093516, 2020). "OVA-sensitized and challenged mice had significantly increased number of BALF inflammatory cell count, particularly eosinophil count, airway hyperresponsiveness, significantly elevated BALF levels of IL-4 and IL-5, and elevated BALF total and OVA-specific IgE." (PMID 32029879, 2020). "HD strongly reduced goblet cell hyperplasia, eosinophil infiltration, and reactive oxygen species (ROS), which reduced airway hyperresponsiveness (AHR), inflammation, and the expression of Th2 cytokines (IL-5 and IL-13) in bronchoalveolar lavage fluid (BALF)." (PMID 30823378, 2019). "In mice, a single antigen challenge has been shown to increase IL-5 protein and mRNA in BALF and lung tissue, with dexamethasone treatment reducing both airway hyperresponsiveness, and IL-5 mRNA in BALF." (PMID 31694631, 2019). "Airway hyperresponsiveness was augmented at a high ventilation rate (120 per minute) in a murine model of ACO, however, lower eosinophil count and the concentration of IL‐5 and IL‐13 in BALF were observed." (PMID 29368450, 2018). "In vivo, intratracheal administration of CD86 siRNA during OVA challenge reduced the production of IL-5, IL-13, and TARC release and ameliorated airway eosinophilia, airway hyperresponsiveness, and elevation of OVA-specific IgE." (PMID 25344652, 2014).